PPARG (peroxisome proliferator activated receptor gamma)
Diseases named in the same sentence as PPARG in open-access papers (continued):
Sharing a sentence is not in itself a finding about the gene and the disease.
Anxiety (31 papers, 2014 to 2025). Intense feelings of nervousness, tension, or panic often arise in response to interpersonal stresses. "The meta-analysis confirmed increased expression of four anxiety-related molecular mediators in response to COVID-19 infection: CALCA, TNF, PLAT, and PPARG, with the latter three associated with neurocognitive decline." (PMID 40766923, 2025). "This is consistent with previous work indicating that PPARγ is critically involved in stress sensitivity and anxiety." (PMID 37479780, 2023). "In this same study, intra-amygdala injections of pioglitazone (PPARγ agonist) were shown to reduce stress-induced anxiety behaviour in rats." (PMID 35335382, 2022). "Peroxisome proliferator-activated receptors (PPARs) are nuclear receptors with three isoforms (PPARα, PPARβ/δ, PPARγ) and can regulate pain, anxiety, and cognition." (PMID 32102354, 2020). "PPARγ agonist treatment provides an effective reduction in pain-related behaviors, including anxiety." (PMID 32138198, 2020). "It is, therefore, likely that PPARγ operates on various cellular levels in modulating anxiety- and depressive-like behavior." (PMID 31319604, 2019). "Chronic stress induced lower PPARγ expression in the adipose tissue and PPARγ knockout mice displayed more anxiety-like behaviors." (PMID 31001073, 2019). "When taking the effects of PPARγ agonists on anxiety and stress into consideration, reaching a conclusion is much more difficult as little comparable evidence is available." (PMID 27433505, 2014). "Furthermore, the genetic deletion of neuronal PPARG has been found to reduce stress-induced anxiety and alleviate the expression of somatic and affective nicotine withdrawal symptoms in animal models." (PMID 40766923, 2025). "This corresponds with earlier research indicating that PPARγ activation may provide protection and alleviate anxiety through the control of neuroinflammatory pathways." (PMID 40863337, 2025). "In addition, the participation of MAO-A was demonstrated by the action of pomegranates in the chronic mild stress model, while the involvement of PPARγ in preventing CAF-anxiety behavior was also reported." (PMID 39204642, 2024). "Interestingly, pomegranates prevented this increase in the inactive form of PPARγ while preventing anxiety." (PMID 39204642, 2024). "For example, PPARγ-KO mice developed enhanced emotional response to stress and exacerbated anxiety." (PMID 37479780, 2023). "As such, Δ9-THC may produce anxiety by activating PPARγ and PPARα in both GABA and glutamate neurons in the amygdala." (PMID 36909477, 2023). "PPARγ agonism was reported to attenuate nicotine withdrawal-induced anxiety and somatic signs, suggesting that PPARγ agonists may have therapeutic potential against substance use disorders." (PMID 37479780, 2023). "In this same investigation, the authors showed that systemic and intra-amygdala injections of pioglitazone (PPARγ agonist) reduced stress-induced anxiety-like behaviour in rats and that these effects were blocked by the administration of the PPARγ antagonist GW9662." (PMID 34072060, 2021). "Specifically, SARS-CoV-2 infection appears to upregulate multiple pro-inflammatory cytokines and secreted proteins (e.g., CALCA, TNF, PLAT, PPARG), which are known to promote anxiety phenotypes, while anxiety itself may modulate key regulators of viral pathophysiology." (PMID 40766923, 2025). "Although much more work needs to be performed in the future, the anxiety- and depressive-like behaviors in seipin-nKO mice, at least partly, relies on the abnormal proliferation and differentiation of adult neural stem and progenitor cells in the hippocampal DG through reduced PPARγ." (PMID 26398946, 2015). "Dysregulated PPARG activity and impaired MME and ACE peptidase expression in the amygdala have been suggested as a possible mechanism leading to pathological anxiety development, with CCK-4 accumulation in the brain being a crucial link." (PMID 40766923, 2025).
Anxiety (continued). "Activation of PPARγ inhibits DA-dependent oICSS, while blockade of PPARα and PPARγ attenuates Δ9-THC-induced reward-attenuation and anxiety but potentiates Δ9-THC-induced hypoactivity and catalepsy." (PMID 37479780, 2023). "Activation of PPARg inhibits DA-dependent oICSS, while blockade of PPARa and PPARg attenuates Δ9-THC-induced reward-attenuation (aversion) and anxiety but potentiates Δ9-THC-induced hypoactivity and catalepsy." (PMID 36909477, 2023). "Moreover, PPARγ agonists attenuated oxidative stress and the behavioral autism-like features in rats treated with valproic or propionic acid, which induce autism-like symptoms, including social impairment, repetitive behavior, hyperactivity, anxiety, and low exploratory activity." (PMID 36768419, 2023). "We note that PPARα/γ agonists or antagonists alone failed to alter basal anxiety levels, while PPARα or PPARγ antagonism only partially reduced Δ9-THC-induced anxiety." (PMID 37479780, 2023). "Both substances are pharmacologically active: THC acts a partial CB1-R agonist, whereas CBD has antagonist/inverse agonist effects at the CB1-R in addition to other anxiety-relevant actions, including effects at TRPV1, 5HT1A-R and peroxisome proliferator-activated receptor gamma (PPAR-γ)." (PMID 36623804, 2023). "Another important finding in this report is that antagonism of PPARα and PPARγ attenuated Δ9-THC-induced anxiety, implicating these receptors in the negative affective properties of cannabinoids." (PMID 36909477, 2023). "The fact that GA is available to the mouse brain and, along with PPARγ, it up-regulates PXR expression of this tissue, suggests other pharmacological applications, including anxiety-like behavior and recognition memory, and blood barrier function modulation that are all PXR-dependent processes." (PMID 32616652, 2020). "Impairments in PPARG regulation and following MME and ACE peptidase expression impairments in amygdala may be the possible mechanism leading to pathological anxiety development, with brain CCK-4 accumulation being a key link." (PMID 33312191, 2020). "In that case, PPARG agonists, such as pioglitazone, may help control UMVI and relieve patient anxiety." (PMID 31915541, 2019). "Moreover, the blockade of PPARα, PPARβ/δ, and PPARγ in the BLA increased innate anxiety status in the absence of pain in NFC rats." (PMID 35335382, 2022). "Genetic deletion of PPARγ triggers anxiety and enhances stress response and PPARγ agonists have anxiolytic properties, although PEA/PPARγ-mediated anxiolysis involves mostly amygdala rather than hippocampus." (PMID 30532004, 2019). "Moreover, while PPARβ/δ and PPARγ blockade or PEA did not modulate pain, cognition- or anxiety-related behaviour, blockade of PPARα exacerbated the CFA-induced impairment of spatial memory and tended to increase anxiety-related responses in the LDB test without affecting mechanical hypersensitivity." (PMID 34072060, 2021).
Arthritis (31 papers, 2006 to 2026). Inflammation of a joint. "BCP prevented inflammation and cartilage damage in an experimental animal model of arthritis by reducing pro-inflammatory cytokines and recovering PPARγ expression." (PMID 33498245, 2021). "Morin, a flavonoid from dietary plants was identified as PPARγ agonist, which attenuates synovial angiogenesis and arthritis via the PPARγ-PTEN-PI3K/Akt pathway." (PMID 32785018, 2020). "Already in the 1990s, it had been reported that PPARγ activation inhibits macrophages/monocytes and the inflammatory cytokine production, which are important for arthritis." (PMID 32785018, 2020). "A recent study in a mouse model of arthritis showed that miR-27a controls arthritis via peroxisome proliferator activated receptor gamma (PPARγ), which also involved a similar set of genes as above." (PMID 30081592, 2018). "Previous studies have demonstrated the anti-inflammatory properties of peroxisome proliferator-activated receptor-gamma (PPARγ) agonists, in experimental models of arthritis and in various inflammatory cells." (PMID 24078927, 2013). "There is evidence suggesting that PPARγ and PPARα agonists attenuate experimentally induced arthritis in murine models." (PMID 23594962, 2013). "The protective effect of PPARγ activators has also been demonstrated in several animal models of arthritis, including a guinea-pig model of OA." (PMID 17386086, 2007). "This is strengthened by the observation that PPARγ haploinsufficiency exacerbates experimentally induced arthritis." (PMID 17386086, 2007). "PPARγ expression can be down-regulated in RA synovial tissue, inhibiting FLS growth and activation in adjuvant-induced arthritis via the Wnt/β-catenin communication pathway." (PMID 39598419, 2024). "Indeed, Δ9-tetrahydrocannabinolic acid (THCA), a phytogenic precursor of THC, exerts anti-arthritis activity through CB1R and PPARγ pathways." (PMID 33498245, 2021). "However, the mechanisms for the beneficial effects of PPARγ agonists in arthritis have not been fully delineated." (PMID 16356194, 2006).
fibrosis (31 papers, 2011 to 2025). the formation of excess fibrous connective tissue in an organ or tissue in a reparative or reactive process. "For bins within PPARG that showed a significant correlation with fibrosis, we compared methylation distributions between high- and low-fibrosis groups within each category." (PMID 40674394, 2025). "PPARγ, mainly expressed by hepatic macrophages, interferes with liver fibrosis progression by regulating macrophage polarization." (PMID 37760020, 2023). "Recently, peroxisome proliferator-activated receptor gamma (PPAR-γ) modulator, GED-0507-34 Levo, reduced EMT progression by reducing EMT-related genes in chronic colitis-associated fibrosis animal models." (PMID 30873033, 2019). "Livers of patients with fibrosis (all F1 apart from 1 patient whom was F2) had up-regulations of PPARG (20%), INSIG1 (39%), SRB1 (11%), NPC1 (13%), and NPC2 (30%) (all P < 0.05)." (PMID 29522534, 2018). "Despite these findings, both the underlying mechanisms for the regulatory effects of PPARγ ligands on intestinal fibrosis and the specific role of PPARγ in this process are unclear." (PMID 28203261, 2017). "miRNAs-dependent PPARγ downregulation in hepatic fibrosis can also occur through indirect mechanisms." (PMID 28167956, 2017). "Quantitative plasma DNA methylation of PPARγ stratified patients into mild (Kleiner 1–2) and severe (Kleiner 3–4) fibrosis (CpG1: 63% vs 86%, p<0.05; CpG2: 51% vs 65% p>0.05)." (PMID 27002005, 2017). "Current studies indicate the role of curcumin in activating PPARγ to intervene TGF-β1/Smads pathway on intestinal fibrosis." (PMID 28203261, 2017). "Specifically, using two CpG sequences previously identified as DMRs in the PPARγ promoter we have shown that hypermethylation at these sequences correlates with advanced fibrosis/cirrhosis." (PMID 27002005, 2017). "In summary, our study showed that curcumin regulated the TGF-β1/Smads pathway by activating PPARγ to improve the intestinal fibrosis." (PMID 28203261, 2017). "PPARγ mutant mice developed significantly more severe cardiac fibrosis to Ang II that correlated with increased expression of profibrotic genes collagen I and collagen III." (PMID 24067190, 2013). "Rat livers exposed to Ad-PPARγ showed significantly less fibrosis than did controls, and overexpression of HNF4α alleviated hepatic fibrosis in rats with bile duct ligation." (PMID 22190905, 2011). "In further analysis when the cohort was segregated into those with mild (F0–1) versus advanced fibrosis (F2–4), carriage of DIO2 rs225014 TT and rs225017 AA, and PPARG rs10865710 CC genotypes were associated with a significantly increased risk of advanced fibrosis, independent of age and gender." (PMID 37059745, 2023). "The mRNA levels of collagen I and collagen III remained consistent, indicating that the PPARγ inhibitor could impair the protective effects of NOB against fibrosis." (PMID 34422028, 2021). "In addition, RSV was reported to inhibit peroxisome proliferator-activated receptor gamma (PPARγ), further attenuating cardiac fibrosis in HG conditions." (PMID 32256959, 2020). "Therefore, it is conceivable that PPARγ activation suppresses cardiac fibrosis by antagonizing inflammatory and hypertrophic signaling pathways." (PMID 27293418, 2016). "In line, heterozygous PPARγ-deficient mice developed more severe MCD-induced NAFLD, whereas treatment with PPARγ agonists, including rosiglitazone and pioglitazone, prevented the development of NAFLD with fibrosis." (PMID 26035752, 2015). "Thus, PPARγ is at least partly involved in the pathogenesis of AF by regulation of inflammation through the NF-κB pathway; PPARγ agonist is potential useful in suppressing cardiac fibrosis and preventing AF occurrence." (PMID 27293418, 2016). "Likewise, PPARγ acts as a modulator of cardiac fibrosis in human as well." (PMID 27293418, 2016).
fibrosis (continued). "In addition to its contribution to improved cardiac function post-MI, PPARγ likely mediated the beneficial effects of QLQX on fibrosis post-MI, because the PPARγ inhibitor blocked the effects of QLQX on cardiac fibrosis as determined by Masson-Trichrome staining." (PMID 25669146, 2015). "Therefore, it raises the topic of combinational therapy in DN in that by synergistically targeting miR-27a/PPARγ/β-catenin and miR-27a/PPARγ/TGF-β signalings, both podocyte injuries and tubulointerstitial fibrosis could be reversed or even prevented." (PMID 28277542, 2017).
hypertriglyceridemia (30 papers, 2007 to 2025). A laboratory test result indicating elevated triglyceride concentration in the blood. "Mechanistically, PPARG polymorphisms lead to abnormal expression of PPARG gene and/or dysfunction of PPARγ protein, causing metabolic disorders such as hypercholesterolemia and hypertriglyceridemia, and thereby increasing susceptibility to CAD." (PMID 35402540, 2022). "Our results showed that the T allele of PPARγ C1431T polymorphism was marginally associated with a lower rate of hypertriglyceridemia in HIV-infected patients receiving anti-retroviral therapy." (PMID 23145084, 2012). "In our study, we found that the T allele of PPARγ C1431T polymorphism was marginally associated with a lower rate of hypertriglyceridemia in HIV-infected patients receiving antiretroviral therapy in univariate and multivariate analyses." (PMID 23145084, 2012). "We hypothesize that decrease in transcription and translation of NCOA3 caused by polymorphism rs2076546 may lead to decrease in PPARγ expression level which may lead to increase in the plasma levels of triglyceride and hypertriglyceridemia." (PMID 26449542, 2015). "Liver-specific deficiency of PPARγ, in the leptin mutant obese mouse (ob/ob), leads to a unique imbalance in triglycerides characterized by low levels of triglycerides in the liver and serum hypertriglyceridemia." (PMID 24130751, 2013). "For the C1431T polymorphism in PPARγ, while patients with the T allele (48.4%) had trends toward lower rate of hypertriglyceridemia, the borderline significance together with insignificant power did not support the protective effect of the T allele against development of hypertriglyceridemia." (PMID 23145084, 2012). "It is easy to understand that PPARG polymorphisms in the promoter region, as well as missense polymorphisms in the exonic region, may cause metabolic disorders such as hypercholesterolemia, hypertriglyceridemia, and hyperglycemia, which subsequently increase the risk of CAD." (PMID 35402540, 2022). "Moreover, hypertriglyceridemia was significantly higher in the PPARG compared to LMNA 482 (p adj = 0.049) and non-482 (p adj = 0.033) groups." (PMID 38887266, 2024). "Numerous studies have reported that E. ulmoides can ameliorate hypertriglyceridemia via up-regulating hepatic α-, β-, and ω-oxidation-related genes in rats and further participate in blood lipid metabolism via regulating the expression of PPARγ." (PMID 38790820, 2024). "Interestingly, differences were observed between the LMNA group and the PPARG group regarding severe hypertriglyceridemia (p adj = 0.015), current HDL-c (p adj = 0.028), and HDL-c lowest (p adj = 0.017)." (PMID 38887266, 2024). "Hypertriglyceridemia may induce anti-inflammatory phenotypic polarization of monocytes and inhibit the release of pro-inflammatory factors through activation of the Peroxisome Proliferator-Activated Receptor Gamma(PPAR-γ) pathway." (PMID 40787234, 2025). "Surprisingly, the insulin resistance, hypertriglyceridemia and liver steatosis in these males could be reversed by PPARγ agonist treatment, demonstrating that PPARγ2 is not essential for TZDs action on insulin sensitivity." (PMID 27483259, 2016).
chronic kidney disease (29 papers, 2007 to 2025). Impairment of the renal function secondary to chronic kidney damage persisting for three or more months. "The transcription factor PPARγ, involved in adipogenesis and lipid metabolism, has been implicated in metabolic diseases such as cardiovascular and chronic kidney diseases." (PMID 40475061, 2025). "The PPARγ agonist rosiglitazone attenuates acute kidney injury in septic rats, and another PPARγ agonist pioglitazone also attenuates cirrhosis-related renal dysfunction and chronic renal insufficiency caused by endotoxemia." (PMID 36420656, 2022). "Pioglitazone is a type of peroxisome proliferator-activated receptor γ (PPARγ) agonist and has been demonstrated to be effective in chronic kidney diseases (CKD) treatment." (PMID 28860994, 2017). "This implies that PPARγ agonists might be effective in the treatment of chronic kidney disease patients." (PMID 31277592, 2019). "Our observations and previous reports suggest that PPARγ agonists might be effective in the future treatment of chronic kidney disease patients, especially in the context of heightened TGF-β1 signaling." (PMID 31277592, 2019). "The regulation of chronic kidney disease (CKD) by HDAC3 appears to involve the peroxisome PPARγ/Klotho pathway." (PMID 39143689, 2025). "BSHX protects 5/6 nephrectomy rats against chronic renal failure probably via regulating the expression of TNF-α, NF-κB, TGF-β1, CTGF, PPARγ, OPN, fibronectin, and laminins and is useful for therapy of CRF." (PMID 24864155, 2014). "In conclusion, BSHX reduces the levels of Scr and BUN, inhibits in situ expression of FN and LN, increases the mRNA expression of PPARγ, and decreases the mRNA expression of TNF-α, NF-κB, OPN, TGF-β1, and CTGF in the kidney tissue of rats with chronic renal failure." (PMID 24864155, 2014). "PPARγ agonists have also been reported to dampen kidney damage in several experimental models such as ischemia reperfusion injury, autosomal dominant polycystic kidney disease (ADPKD), and nondiabetic chronic kidney diseases." (PMID 37958504, 2023). "Moreover, PPARγ agonists have been also shown to reduce renal damage in animal models of ischemia reperfusion injury, autosomal dominant polycystic kidney disease (ADPKD) or nondiabetic chronic kidney diseases." (PMID 31277592, 2019).